FOXK2 (forkhead box K2)
Description:
Transcriptional regulator involved in different processes such as glucose metabolism, aerobic glycolysis and autophagy. Recognizes and binds the forkhead DNA sequence motif (5'-GTAAACA-3') and can both act as a transcription activator or repressor, depending on the context. Together with FOXK1, acts as a key regulator of metabolic reprogramming towards aerobic glycolysis, a process in which glucose is converted to lactate in the presence of oxygen (By similarity). Acts by promoting expression of enzymes for glycolysis (such as hexokinase-2 (HK2), phosphofructokinase, pyruvate kinase (PKLR) and lactate dehydrogenase), while suppressing further oxidation of pyruvate in the mitochondria by up-regulating pyruvate dehydrogenase kinases PDK1 and PDK4 (By similarity). Probably plays a role in gluconeogenesis during overnight fasting, when lactate from white adipose tissue and muscle is the main substrate (By similarity). Together with FOXK1, acts as a negative regulator of autophagy in skeletal muscle: in response to starvation, enters the nucleus, binds the promoters of autophagy genes and represses their expression, preventing proteolysis of skeletal muscle proteins (By similarity). In addition to the 5'-GTAAACA-3' DNA motif, also binds the 5'-TGANTCA-3' palindromic DNA motif, and co-associates with JUN/AP-1 to activate transcription. Also able to bind to a minimal DNA heteroduplex containing a G/T-mismatch with 5'-TRT[G/T]NB-3' sequence. Binds to NFAT-like motifs (purine-rich) in the IL2 promoter. Positively regulates WNT/beta-catenin signaling by translocating DVL proteins into the nucleus. Also binds to HIV-1 long terminal repeat. May be involved in both positive and negative regulation of important viral and cellular promoter elements. Accessory component of the polycomb repressive deubiquitinase (PR-DUB) complex; recruits the PR-DUB complex to specific FOXK2-bound genes.
Synonyms: nGTBP; ILF; ILF1; ILF-1
Tractability: PROTAC: UniProt records ubiquitination sites on it; ubiquitination databases record sites on it; its protein half-life has been measured.
Gene: Protein-coding gene on chromosome 17 (82,519,689 to 82,644,662, forward strand). Ensembl gene ENSG00000141568.
Subcellular location: Nucleus; Cytoplasm
Subcellular location (Human Protein Atlas): Nucleoplasm; Mitochondria; Vesicles
Pathways (Reactome):
Metabolism of proteins: UCH proteinases
Gene Ontology:
Molecular function: DNA-binding transcription activator activity, RNA polymerase II-specific; magnesium ion binding; protein binding; RNA polymerase II cis-regulatory region sequence-specific DNA binding; sequence-specific DNA binding; transcription cis-regulatory region binding; DNA-binding transcription factor activity; DNA-binding transcription factor activity, RNA polymerase II-specific; DNA-binding transcription repressor activity, RNA polymerase II-specific
Biological process: negative regulation of DNA-templated transcription; positive regulation of DNA-templated transcription; positive regulation of transcription by RNA polymerase II; canonical glycolysis; intracellular glucose homeostasis; negative regulation of autophagy; regulation of DNA-templated transcription; regulation of glucose metabolic process; regulation of transcription by RNA polymerase II; response to starvation; negative regulation of transcription by RNA polymerase II
Cellular component: nucleoplasm; nucleus; chromatin; cytoplasm; mitochondrion
Genetic constraint (gnomAD): Loss-of-function variants: 23 observed, 45.18 expected, observed/expected ratio (o/e) 0.51, 90% interval 0.37 to 0.72. The synonymous counts are far from expectation, so gnomAD's model fits this gene poorly and the ratio says little. Missense variants: 920 observed, 815.3 expected, observed/expected ratio (o/e) 1.13, 90% interval 1.07 to 1.19. Synonymous variants: 489 observed, 361.19 expected, observed/expected ratio (o/e) 1.35, 90% interval 1.26 to 1.46.
Homologues: Orthologues: macaque FOXK2 (98% identical), dog FOXK2 (93% identical), mouse Foxk2 (93% identical), pig FOXK2 (93% identical), guinea pig FOXK2 (86% identical), rat Foxk2 (81% identical), rabbit FOXK2 (78% identical), tropical clawed frog foxk2 (77% identical), chimpanzee FOXK2 (72% identical), zebrafish foxk2b (69% identical), zebrafish foxk2a (62% identical). Paralogues in human: FOXK1 (54% identical), FOXJ3 (15% identical), FOXD2 (15% identical), FOXN1 (15% identical), FOXC1 (14% identical), FOXD3 (14% identical), FOXJ1 (14% identical), FOXC2 (14% identical), FOXD1 (14% identical), FOXA1 (14% identical), FOXJ2 (14% identical), FOXD4 (13% identical), and 29 more.
Diseases named in the same sentence as FOXK2 in open-access papers:
FOXK2 is named in the same sentence as 74 diseases in open-access papers, as found by Europe PMC text mining. Sharing a sentence is not in itself a finding about the gene and the disease. The quoted sentences say what the papers report.
breast carcinoma (21 papers, 2015 to 2025). "As breast cancer progresses, there is a gradual loss of FOXK2 expression, leading to the activation of the hypoxia pathway and an increase in the expression of enhancer of EZH2." (PMID 38741782, 2024). "FOXK2 regulates the downstream gene FBXO32 in breast cancer and then activates ribosome‐associated pathways to promote tumor cell proliferation." (PMID 39552461, 2024). "According to the analysis of TCGA data set, the frequency of FOXK2 changes in melanoma patients is the highest (>6%), and the mutation rate of breast cancer also ranks in the top six (>4%)." (PMID 39552461, 2024). "On the other hand, FOXK2 was shown to act as a tumor suppressor in estrogen receptor–positive breast cancer by interacting with multiple corepressor complexes, causing suppression of cell proliferation and metastasis." (PMID 35349489, 2022). "In agreement with the findings in breast cancer, FOXK2 has been implicated in suppressing tumorigenesis in clear-cell renal cell carcinoma." (PMID 30897782, 2019). "For instance, during breast cancer progression, there is a progressive loss of FOXK2 expression, which correlates closely with poor prognostic indicators such as higher histological grade, lymph node positivity, and ERα−/PR−/HER2− status, highlighting its potential as a prognostic biomarker." (PMID 38741782, 2024). "Recently, FOXK2 has also been implicated in mediating breast cancer drug action." (PMID 29540677, 2018). "We show here that FOXK2 regulates FOXO3a to modulate drug sensitivity and that deregulation of expression and activity of FOXK2 confers paclitaxel and epirubicin resistance and associates with a poor clinical outcome in breast carcinoma patients." (PMID 26344694, 2015). "While ERα is a crucial regulator of breast cancer progression, FOXK2 can repress its function via enhancing ERα ubiquitin-mediated degradation." (PMID 40003882, 2025). "Associated with multiple transcription corepressor complexes, FOXF2 can repress the tumorigenesis and hypoxic response of breast cancer, and during the progression of breast cancer, FOXK2 expression is progressively lost." (PMID 40003882, 2025). "The analysis of patient samples shows that high FOXK2 expression is related to tumor proliferation of breast cancer and ACC." (PMID 39552461, 2024). "Although FOXK2 is recognized as an oncogene in colorectal cancer and hepatocellular carcinoma, it acts as a tumor suppressor in breast cancer, cervical cancer, and non-small cell lung cancer (NSCLC)." (PMID 38741782, 2024). "FOXK2 was shown to promote tumor progression by activating Wnt signaling in colon cancer but suppressed ER–positive breast cancer cell proliferation by interacting with transcriptional corepressor complexes." (PMID 38734828, 2024). "FOXK2 acts as a suppressor in breast cancer, renal clear cell carcinoma, non-small cell lung cancer, and glioma but has oncogenic roles in colon cancer, colorectal cancer, and hepatocellular carcinoma." (PMID 38734828, 2024). "For example, this article starts with pan‐cancer and finally focuses on FOXK2 and breast cancer related prognosis." (PMID 39552461, 2024). "FOXK2 can reportedly suppress tumor progression in breast cancer, renal carcinoma, and glioma, while contrasting findings have been reported for colorectal cancer and HCC." (PMID 36922872, 2023). "Studies have shown that FOXK2 can inhibit the proliferation and metastasis of breast cancer in vivo and in vitro." (PMID 35903069, 2022). "FoxK2 can inhibit the proliferation and invasion of breast cancer cells and suppress the growth and metastasis of breast cancer." (PMID 35903069, 2022). "Corroborating these data, a separate study reported that FOXK2 mediates the cytotoxic effects of chemotherapeutic agents (paclitaxel and epirubicin) on breast cancer cells." (PMID 36172141, 2022). "The authors found that FOXK2 inhibited the proliferation and invasion of breast cancer cells and suppressed the growth and metastasis of breast cancer." (PMID 36172141, 2022).
breast carcinoma (continued). "SUMOylation of FOXK2 has also been shown to result in FOXK2‐induced apoptosis in breast cancer cells." (PMID 34866322, 2022). "Chemotherapy is essential for improving outcomes (eg preventing or decreasing recurrence, progression and metastasis) in patients with cancer, and FOXK2 has been shown to reduce the chemosensitivity of paclitaxel in breast cancer cells." (PMID 34866322, 2022). "Recently, sumoylation (Lys 527 and Lys633) was associated with the regulation of FOXK2 activity, and its role in mediating the cytotoxic response to paclitaxel through the tumor suppressor FOXO3 in breast cancer cells was recently reported." (PMID 36172141, 2022). "Cloning and cell viability analysis showed that enhanced FoxK2 expression sensitized McF-7 breast cancer cells to paclitaxel or epirubicin treatment while depletion of FoxK2 through small interfering RNA (siRNA) resulted in resistance." (PMID 35903069, 2022). "FOXK2 nuclear expression correlates with FOXO3a expression and clinical outcomes in patients with breast cancer." (PMID 36172141, 2022). "In breast cancer, FoxK1 has both stimulatory and inhibitory effects, while FoxK2 has inhibitory effects." (PMID 35903069, 2022). "Some studies have shown that the expression of FOXK2 is gradually lost during breast cancer development." (PMID 36172141, 2022). "It was reported that FOXK2 inhibited cell proliferation and invasion in breast cancer, non-small cell lung cancer (NSCLC), clear-cell renal cell carcinoma, gastric cancer, and indicated favorable prognosis." (PMID 33785763, 2021). "In this context, FOXK2-mediated cytotoxic effects in breast cancer cells have been demonstrated to be stimulated by SUMOylation, in a study which identified two consensus SUMOylation motifs within the FOXK2 sequence." (PMID 30897782, 2019). "Interestingly, FOXK2 expression is correlated with reduced disease-free survival in breast cancer patients, consistently with the in vitro data supporting the hypothesis that constitutively high expression levels of nuclear FOXK2 are closely associated with poor clinical outcome and drug resistance." (PMID 30897782, 2019). "Nevertheless, Shan and colleagues found FOXK2 expression downregulated in breast carcinomas comparatively to their adjacent tissues and correlated this with better survival curves." (PMID 30897782, 2019). "In breast cancer patient samples, FOXK2 expression has been analyzed by immunohistochemistry and around 50% positivity has been found." (PMID 30897782, 2019). "One of the first studies on the role of FOXK2 in cancer showed that it interacts with estrogen receptor alpha (ERα), a master regulator of breast cancer development." (PMID 30897782, 2019). "Corroborating these data, another study has shown that FOXK2 can mediate the cytotoxic effects of chemotherapeutic agents in breast cancer cells." (PMID 30897782, 2019). "In conclusion, our study demonstrates that FOXK2 SUMOylation plays a crucial role in mediating the cellular cytotoxic function of paclitaxel in breast cancer cells." (PMID 29540677, 2018). "Taken together, our findings suggest that inhibition of SUMOylation modulates the role of FOXK2 in paclitaxel response and suppresses its transcriptional activity of FOXK2 in breast cancer cells." (PMID 29540677, 2018). "The forkhead transcription factor FOXK2 plays a critical role in suppressing tumorigenesis and mediating cytotoxic drug action in breast cancer." (PMID 29540677, 2018). "In this study, we investigated the role of SUMOylation in the regulation of FOXK2 and its role in modulating drug sensitivity in breast cancer." (PMID 29540677, 2018). "In breast cancer, FOXK2 has been demonstrated to downregulate ERα protein stability and transcriptional activity, resulting in decreased cell growth." (PMID 29540677, 2018). "Next, we tested the role of FOXK2 SUMOylation in mediating the cytotoxic function of paclitaxel in breast cancer cells." (PMID 29540677, 2018).
breast carcinoma (continued). "We identified FOXK2 as a key mediator of the cytotoxic function of paclitaxel and epirubicin as well as a modulator of drug sensitivity in breast cancer." (PMID 26344694, 2015). "In order to examine the relationship between FOXK2 and ERα in breast cancer, we compared the protein levels of FOXK2 and ERα in the breast cancer specimens." (PMID 25740706, 2015). "Collectively, these findings suggest that FOXK2 targets FOXO3a expression in breast cancer cells to enhance sensitivity to paclitaxel." (PMID 26344694, 2015). "This corroborates the finding from the breast cancer cell lines and further suggests that FOXK2 directly regulates FOXO3a transcription." (PMID 26344694, 2015). "This negative regulation of ERα by FOXK2 would disrupt the ERα-mediated cell growth, and in the case of breast cancer cells, it would mean a reduction in cell proliferation and possibly, the spread of cancer cells." (PMID 25740706, 2015). "In this study, we focused on the role of FOXK2 in ERα-positive breast cancer cells as this would allow us to investigate the connection between FOXK2 and ERα in breast cancer and to interpret this connection in terms of its significance in biological function." (PMID 25740706, 2015). "The significance of FOXK2 in survival analyses provides further evidence for its involvement in breast cancer progression and drug response." (PMID 26344694, 2015). "Here we demonstrate that FOXK2 has a central role in mediating the cytotoxic drug response in breast cancer." (PMID 26344694, 2015). "Consistent with our finding from the breast cancer cell lines that FOXK2 expresses primarily in the nucleus, all the patients had predominantly nuclear FOXK2 expression." (PMID 26344694, 2015). "In this study, we examined the role and regulation of FOXK2 in mediating the cell proliferation and chemotherapeutic drug response in breast cancer." (PMID 26344694, 2015). "Clonogenic and cell viability assays showed that enhanced FOXK2 expression sensitizes MCF-7 breast cancer cells to paclitaxel or epirubicin treatment, whereas FOXK2 depletion by small interfering RNAs (siRNAs) confers drug resistance." (PMID 26344694, 2015). "The physiological importance of the regulation of FOXO3a by FOXK2 is further confirmed by the significant correlations between FOXO3a and FOXK2 expression in breast carcinoma patient samples." (PMID 26344694, 2015). "We also examined the protein levels of endogenous ERα and FOXK2 in various breast cancer cell lines." (PMID 25740706, 2015). "FOXK2 SUMOylation also plays a role in breast cancer treatment." (PMID 38741782, 2024). "In breast cancer cells, FOXK2 is positively regulated by estrogen receptor alpha (ERα)." (PMID 38741782, 2024). "Similar to its role in breast cancer, FOXK2 has been implicated in suppressing tumorigenesis in non-small-cell lung cancer (NSCLC)." (PMID 36172141, 2022). "Conversely, FoxK2 plays a central role in the cytotoxic drug responses in breast cancer." (PMID 35903069, 2022). "In breast cancer, lung cancer, and glioma, FOXK2 performs tumor suppressor activity that may correspond to its mutation in the context of this fusion gene." (PMID 36009586, 2022). "In breast cancer, FOXK2 could regress various genes containing HIF1β and EZH2, which further inhibited the hypoxia-induced response and tumor carcinogenesis." (PMID 33313412, 2020). "In ERα-positive breast cancer, FOXK2 could inhibit tumor growth via decreasing the ERα stability through BRCA1/BARD1-associated mechanisms." (PMID 33313412, 2020). "FOXK2 could suppress cell proliferation and invasion in clear-cell renal cell carcinoma and breast cancer and inhibit tumor growth in breast cancer." (PMID 33313412, 2020). "FOXK2 also regulated the sensitivity of breast cancer to epirubicin and paclitaxel." (PMID 33313412, 2020).